IL33 (interleukin 33)
Diseases named in the same sentence as IL33 in open-access papers (continued):
Sharing a sentence is not in itself a finding about the gene and the disease.
cancer (continued). "In gastric cancer cells, upregulation of TTP inhibits the proliferation, invasion, and migration of cancer cells by negatively correlating with IL-33 expression." (PMID 34026612, 2021). "Further, PPARγ blockade in ILC2s disrupts their pro-tumoral effect induced by IL-33-secreting cancer cells." (PMID 33953160, 2021). "IL-33 binds and activates its receptor IL-1 receptor-like 1 (IL1RL1/ST2) and is associated with inflammation and cancer progression." (PMID 34063627, 2021). "A better understanding of the distinct roles of IL-33 in epithelial, stromal, and immune cell compartments will benefit the development of a targeting strategy for this IL-33/ST2 axis for cancer immunotherapy." (PMID 34209038, 2021). "Nevertheless, these data demonstrate the exploitation of the IL-33/ST2 axis as a promising target of cancer immunotherapy." (PMID 34209038, 2021). "Platelet-derived growth factor (PDGF)-BB secretion by cancer cells induces IL-33 expression and secretion by pericytes and CAFs via a PDGF receptor β (PDGFRβ)–dependent mechanism." (PMID 33783686, 2021). "Instead of functioning initially as an important inflammatory cytokine, the CAF-induced IL-33 expression was responsible for enhancing cancer cell progression via a paracrine effect." (PMID 34298657, 2021). "Several studies have revealed that elevated IL‐33 levels are probable prognostic markers and correspond to poor prognosis in many types of cancers." (PMID 33305406, 2021). "Consistent with prior reports on cancer cells and fibroblasts, we have identified that IL-33/ST2 signaling is accompanied by increased metabolic (particularly glycolytic) activity." (PMID 33884963, 2021). "Once activated by IL-33, eosinophils adhered to cancer cells via CD11b/CD18 and degranulated lytic molecules through their convergence to immunological synapses." (PMID 34209038, 2021). "The role of IL-33 in cancer is most likely context-dependent because it demonstrates either an anti-tumorigenesis effect (e.g., pancreatic cancer, ovarian, and colon cancer) or a pro-tumorigenesis effect (e.g., breast cancer, lung cancer)." (PMID 34572318, 2021). "Group 2 innate lymphoid cells (ILC2s) play a critical role in protection against helminths and in diverse inflammatory diseases by responding to soluble factors such as the alarmin IL-33, that is often overexpressed in cancer." (PMID 33953160, 2021). "High numbers of ILC2 can be found in many IL-33-enriched tumors, although their role in cancer immunity remains controversial." (PMID 33329534, 2020). "In an orthotopic PDAC model, IL-33 drives ILC2 to enable tissue-specific cancer immunity, namely by increasing intratumor activated CD8+ T cells and DCs." (PMID 33261061, 2020). "The clinicopathological correlations and survival analyses of the patients with their IL-33 levels were performed and the data revealed the combined IL-33 from cancer cells and CAFs as a good prognosis marker in CCA patients." (PMID 33046978, 2020). "It is possible to conclude that a high level of IL-33 which can be released from either cancer cells or CAFs is correlated with patient good prognosis." (PMID 33046978, 2020). "This is partly supported by the in vitro findings that high intracellular IL-33 suppressed cancer cell migration and exogenous high IL-33 inhibited cancer cell migration." (PMID 33046978, 2020). "Recent discoveries have further suggested that IL-33 can induce the proliferation, survival, and metastasis of cancer cells." (PMID 32363166, 2020). "The immunohistochemical staining results revealed that cancer cells were the major source of IL-33 in CCA tissues and cytoplasmic localization was detected." (PMID 33046978, 2020). "Although CD44 and IL-33/ST2 have been well documented in human cancer metastasis or prognosis, respectively, evidence of the CD44 gene SNPs combined with IL-33/ST2 pathway functional polymorphisms in HCC susceptibility and clinical characteristics is scarce." (PMID 33062675, 2020).
cancer (continued). "All 91 patients expressed IL-33 in cancer cells in which 53% (48/91) had high levels and 47% (43/91) had low levels." (PMID 33046978, 2020). "In CCA, IL-33 has been reported as a cancer promoter in an experimental mouse model 20-22, but its impact in human CCA is still controversial." (PMID 33046978, 2020). "Blood vessel generation facilitates the infiltration of cancer exacerbating cells, including but not limited to, myeloid derived suppressor cells and M2s, upon which IL-33 is able to further exert effect." (PMID 32363166, 2020). "IL33 expression correlates with poor prognosis in some cancers, but predicts good outcomes in others." (PMID 32719677, 2020). "The combination of IL-33 levels in cancer cells and CAFs (cancer cells/CAFs) was divided into 4 groups depending high (CH) or low (CL) levels in cancer cells and either presence (FP) or absence (FA) in CAFs included CH/FP, CH/FA, CL/FP, and CL/FA patterns." (PMID 33046978, 2020). "Interleukin-33 (IL-33), a member of IL-1 family, plays a vital role in different inflammatory diseases and cancer." (PMID 31979178, 2020). "In this review, we integrate the outcomes of recent studies on the role of MCs and IL33 in cancer with our own observations in the GI tract." (PMID 32719677, 2020). "We also demonstrated that EMT, a critical cellular process to cancer metastasis, is induced by stromal IL-33." (PMID 31659258, 2020). "In cancer immunity, IL-33 can display both pro-tumoral and anti-tumoral functions, depending on the specific microenvironment." (PMID 33329534, 2020). "The IL-33/ST2 axis has a controversial role in cancer immunity, since both pro- and anti-tumoral functions have been reported." (PMID 33329534, 2020). "Mean survival time of patients with low levels of IL-33 in cancer cells (CL) was 806 ± 158 days compared with 1,747 ± 196 days in patients with a high level of IL-33 in cancer cells (CH)." (PMID 33046978, 2020). "We discuss how these opposing responses affect the therapeutic potential of targeting MC and IL33, and highlight the caveats and challenges facing our ability to effectively harness MCs and IL33 biology for anti-cancer immunotherapy." (PMID 32719677, 2020). "Diverse functions for both IL33 and mast cells were uncovered in the context of cancer initiation and progression." (PMID 32719677, 2020). "Nevertheless, there is significant evidence of the role of MCs and IL33 in late stage cancers, particular in the context of tissue remodeling, epithelial to mesenchymal transition and invasion." (PMID 32719677, 2020). "The increased expression levels of IL-33 in cancer cells were detected and compared to those in normal bile duct epithelial cells." (PMID 33046978, 2020). "In conclusion, the combination of high IL-33 level in cancer cells and CAFs is a potentially good prognosis marker in CCA patients." (PMID 33046978, 2020). "In this work, patients with the combination of high IL-33 in cancer cells and the presence of IL-33 in CAFs had a significantly long survival time." (PMID 33046978, 2020). "Due to its pleiotropic effects, IL-33 plays an important role in tissue homeostasis, infection, inflammation and cancer." (PMID 33634017, 2020). "The combined high IL-33 inside the cancer cells with the presence of IL-33 in CAFs is a promising marker for good prognosis in CCA patients." (PMID 33046978, 2020). "The modulation of these and other checkpoint molecules by IL-33 and the immune targets in each cancer type remain to be fully elucidated." (PMID 33329534, 2020). "The various intensities of IL-33 in cancer cells were detected from low to high while the pattern in stromal fibroblasts was presented as either positive (arrows) or negative staining." (PMID 33046978, 2020). "There is a strong correlation between the level of IL-33 and the progression of disease in a variety of malignant epithelial tumors." (PMID 33062675, 2020).
cancer (continued). "While some researches demonstrate that IL-33/Treg axis has favouring effects on cancer, IL-33 signaling onto CD8+ T cells and NKs can be antitumorigenic." (PMID 31736655, 2019). "The alarmin IL-33 has recently gained importance as an indicator of tissue damage and prognostic marker for the prognosis of cancer diseases." (PMID 31396219, 2019). "IL-33 is regarded as an “alarmin” able to stimulate several effectors of the immune system, regulating numerous immune responses comprising cancer immune reactions." (PMID 31652497, 2019). "In parallel with other IL-1 family members, both pro- and anti-tumorigenic roles have been reported for IL-33 in cancer." (PMID 31231372, 2019). "In this cancer type, administration of IL-33 promotes cancer cell migration and invasion through induction of EMT." (PMID 31231372, 2019). "In cancer, the role of IL‐33 remains controversial, with both pro‐tumorigenic and anti‐tumorigenic effects reported across different cancer types and cellular sources." (PMID 31032905, 2019). "Autocrine production of IL-33 has been suggested to contribute to human cancer cell survival, migration and resistance to chemotherapy, through the up-regulation of anti-apoptotic proteins including Bcl-2, and via ST2/STAT3." (PMID 31535033, 2019). "The majority of the studies mentioned propose cancer immunotherapy strategies based on exogenous IL-33 administration." (PMID 30416507, 2018). "IL-33 has a significant role in cancer immune-surveillance in primary prostate and lung tumors, which can be lost during the metastatic transition inducing immune escape." (PMID 30416507, 2018). "Previous studies of this cytokine in cancers mainly focused on its regulation on immune responses by which IL-33 modulated cancer progression." (PMID 30119635, 2018). "This review therefore summarizes the dual role of this cytokine in cancer and suggests that new proposals for IL-33-based cancer immunotherapies should be considered with caution." (PMID 30416507, 2018). "As mentioned in the introduction, IL-33-activated DC are also able to promote the differentiation of TH17 cells which play an important role in cancer development." (PMID 30416507, 2018). "The Cancer Genome Atlas Pan-Cancer analysis project showed and declared that the level of IL-33 expression is altered in only 3% of ~580 tumors and that the most common genetic alteration is the deletion of the IL-33 gene." (PMID 30416507, 2018). "The relevance of IL-33-mediated mast cell response has been found also in vivo in several pathological conditions, including cancer." (PMID 30483263, 2018). "IL-33 is a candidate cytokine for immunotherapy that can activate T lymphocytes and modulate antitumor immunity in some cancers." (PMID 29896199, 2018). "These properties therefore position IL-33 as a possible inducer and prognostic marker of cancer development, as reviewed here." (PMID 30416507, 2018). "In other clinical conditions, increased IL-33 expression was inversely correlated with the overall survival of cancer patients." (PMID 30483263, 2018). "Evidence indicates that IL-33 is a possible inducer of and prognostic marker for cancer development." (PMID 30112116, 2018). "Accumulating evidence has demonstrated that JNK plays an important role in the biological actions of IL-33 in the normal cells and the cancer cells." (PMID 29373608, 2018). "Inhibition of IL-33 diminished the CAF-induced aggressive behavior of HNPCC while administration of IL-33 promoted cancer cell invasion and migration by inducing epithelial to mesenchymal trans differentiation and increased IL-33 expression in cancer cells." (PMID 30205617, 2018). "There is abundant evidence indicating that IL-33/ST2 signaling induces the expression of cytokines that orchestrate many aspects of cancer pathology including angiogenesis, invasiveness, immune protection, and metastasis." (PMID 30205617, 2018).
cancer (continued). "In the future, IL-33 targeting in cancer immunotherapies should be considered with caution, especially taking into account the intricate dual role of this cytokine in cancer as shown in this review." (PMID 30416507, 2018). "Understanding of direct and indirect effects of IL-33 would be important for profound therapeutic implications, especially in the realm of cancer immunotherapy." (PMID 30619376, 2018). "Evidences pointed out IL-33 as a possible inducer and prognostic marker of cancer metastasis by way of mechanisms like immune regulation, with intensive cytotoxic activities of NK cells and increased systemic Th1 and Th17 cytokines." (PMID 30619376, 2018). "Interleukin-33 (IL-33) is a pro-inflammatory cytokine and it is involved in the development of chronic inflammation and cancer." (PMID 30426271, 2018). "This intratumoral IL-33 is expressed by cancer cells as well as by other cell components of the TME." (PMID 30416507, 2018). "A direct effect on colorectal epithelial cells: A direct promoting effect of IL-33 on cell transformation has been observed in other types of human cancers." (PMID 30547011, 2018). "Patients exhibiting a low invasion pattern grading score (IPGS) were associated with low or no expression of IL-33, whereas patients exhibiting a high IPGS displayed over-expression of IL-33 in both CAFs and cancer cells." (PMID 30205617, 2018). "Collectively, these data support the conclusion that the presence of ILC2s is important in limiting metastases and that ILC2s participate in cancer immune-surveillance through an IL-33/ILC2 axis." (PMID 29440650, 2018). "This review begins from a summarized introduction of IL-33, to its remarkable implications and molecular transduction pathway in malignant neoplasms, ends with latest inspiration for IL-33 in treatment." (PMID 30619376, 2018). "Although IL-33 functioned pro-tumorigenically in various cancers, for some cancer types the findings so far are controversial." (PMID 30619376, 2018). "For each type of cancer, we discuss the pro-tumorigenic role of IL-33/ST2 signaling, and, unless discussed in historic terms, this is followed by its anti-tumorigenic role in cases where opposing roles have been reported." (PMID 30205617, 2018). "Here, we review the sometimes opposing roles of the IL-33/ST2 axis as studied thus far in different types of cancers." (PMID 30205617, 2018). "This knowledge will facilitate the development of therapies targeting IL-33/ST2 to block cancer progression or as adjuvant therapy to enhance immunotherapies against cancer." (PMID 30205617, 2018). "These conclusions are supported by Wasmer and Krebs' review who demonstrated the multiple functions of IL-33 in different cancer types." (PMID 30416507, 2018). "This infiltrating IL-33 has a direct pro-tumorigenic effect on cancer cells and indirect effects on cellular components of the TME." (PMID 30416507, 2018). "In all, it is important to understand the mechanisms by which IL-33 impacts the development and malignancy of different types of cancers." (PMID 30205617, 2018). "We examine the impact of these observations on targeting IL-33/ST2 in therapeutic applications for the treatment or management of cancer progression." (PMID 30205617, 2018). "Stroma-derived IL-33 drove CRC neoplastic transformation from adenoma to carcinoma by promoting angiogenesis." (PMID 30119635, 2018). "Serum IL-33 levels were significantly higher in patients with carcinomas as compared to those with benign breast cancer." (PMID 30205617, 2018). "IL-33 is expressed in high levels in cancer cells from NSCLC patients, supporting NSCLC outgrowth and metastasis." (PMID 28978138, 2017). "We would like to point out that there are some studies showed an anti-cancer activity of IL-33 using established cancer cell lines and murine models." (PMID 28978138, 2017).
cancer (continued). "IL33 is a cytokine involved in a spectrum of biological processes, and the chronic inflammatory signaling activation is known to be involved in cancer progression." (PMID 29285217, 2017). "Our previous study unraveled a pro-cancer function of IL-33 in fueling outgrowth and metastasis of human NSCLC cells." (PMID 28978138, 2017). "IL-33 is thought to be a dangerous signal of malignant tumor, but the role of IL-33 in tumors is complicated that some researchers even hold the opposite view." (PMID 28402273, 2017). "Preliminary evidence suggesting the involvement of IL-33 and Th2-like cells in other forms of cancer was provided by studies in models of liver disease in which inflammation and fibrosis can result in cancer." (PMID 27882334, 2016). "In the cancer group, we found that the serum level of IL-33 was higher than in controls (P < 0.0001)." (PMID 27340318, 2016). "Overall, these data demonstrated that TTP inhibits cell migration and invasion of GC in vitro, and that IL-33 is involved in the TTP-mediated suppression of cancer metastasis." (PMID 27074834, 2016). "Except for a few particular examples presented above, IL-33 has mainly a pro-tumorigenic function for cancer development." (PMID 28119694, 2016). "Another level of complexity comes from the observation that the IL-33/ST2 pathway appears to be differently regulated during the progression of distinct types of cancers, as mentioned just above." (PMID 28119694, 2016). "Previous researches illustrated that the elevated serum IL-18 played an important role in a variety of cancers, and a similar function of IL-33 is still under debate." (PMID 27340318, 2016). "These CAFs release IL-33, which induces epithelial-to-mesenchymal transition of cancer cells, thereby supporting their ability for migration and invasion." (PMID 28119694, 2016). "We identified IL-33 to be important for the immune recognition of murine lung, human kidney renal clear cell and in human and murine prostate, carcinomas." (PMID 27619158, 2016). "First, we identify that IL-33 expression is reduced in many carcinomas upon their transition to the metastatic form of disease." (PMID 27619158, 2016). "Sun et al34 observed a positive correlation between IL33 serum levels and cancer severity, with individuals with the highest IL33 serum levels having the most aggressive cancers with metastatic properties." (PMID 28210674, 2015). "In summary, this study indicated that serum IL-33 is higher in cancer patients compare to patients with BBD." (PMID 24778632, 2014). "We found significantly higher serum levels of IL-33 in patients with BC, compared with patients with BBD, and higher expression of IL-33 in carcinomas and adjacent tissues to tumors, compared with normal breast tissue from the same patients." (PMID 24778632, 2014). "Of interest is that serum levels and carcinoma tissue expression of IL-33 are higher in patients with a family history of malignant breast carcinoma." (PMID 24778632, 2014). "Thus, targeting IL-33 and its downstream signaling pathways represents a promising therapeutic approach for cancer treatment." (PMID 40647388, 2025). "Thus, the IL-33/Treg axis plays a critical role in mediating cancer development in the liver exposed to HBV plus carcinogens." (PMID 40579434, 2025). "Owing to the dysregulation of mechanisms involved in cell death in patients with cancer, downstream IL-33 maturation may also be affected by alterations in caspase activity." (PMID 39925809, 2025). "As cancer research advances, the IL-33/ST2 signaling pathway’s role in cancer has gained attention." (PMID 39925809, 2025). "In addition to its pro‐inflammatory effects, IL‐33 has also been reported to be involved in remodeling the immune microenvironment, influencing angiogenesis, and directly regulating the phenotypes of cancer cells." (PMID 40860436, 2025). "IL-33 functions as a cytokine and a nuclear protein to initiate chronic inflammation and cancer." (PMID 40647388, 2025).